TDP1 (tyrosyl-DNA phosphodiesterase 1)
Diseases named in the same sentence as TDP1 in open-access papers (continued):
Sharing a sentence is not in itself a finding about the gene and the disease.
spinocerebellar ataxia with axonal neuropathy type 1 (4 papers, 2014 to 2025). "Spinocerebellar ataxia with axonal neuropathy type 1 (OMIM: 607250) is an extremely rare autosomal recessive disorder caused by a mutation in the tyrosyl-DNA phosphodiesterase 1 (TDP1) gene." (PMID 39576382, 2024). "The His493Arg mutation in Tdp1 gene causes spinocerebellar ataxia with axonal neuropathy type 1 (SCAN1) by affecting neuronal cells." (PMID 33425909, 2020). "Spinocerebellar ataxia with axonal neuropathy type 1 (SCAN1), is caused by the homozygous H493R mutation in tyrosyl-DNA phosphodiesterase 1 (TDP1), an enzyme that initiates the repair of DNA topoisomerase 1 (TOP1)-induced SSBs by unlinking the TOP1 peptide from the break." (PMID 41315253, 2025).
colon carcinoma (3 papers, 2014 to 2020). "In colon cancer, TDP1 depletion increased the sensitivity to irinotecan in a TOP1-dependent manner." (PMID 32028591, 2020). "Processing of 3′-PG termini was also examined in TDP1-knockdown HCT116 colon carcinoma cells." (PMID 24371269, 2014).
non-small cell lung carcinoma (3 papers, 2014 to 2023). A group of at least three distinct histological types of lung cancer, including non-small cell squamous cell carcinoma, adenocarcinoma, and large cell carcinoma. "The relevance for TDP1 targeting in anticancer treatment is supported by different studies finding that TDP1 activity is upregulated from normal to tumor tissue in samples from non-small-cell lung cancer patients and that loss of TDP1 sensitizes cancer cells to different anticancer drugs." (PMID 34300575, 2021). "Overexpression of TDP1 increases resistance to CPT and increased expression of TDP1 protein resulting in increased enzyme activity has been observed in a set of non-small-cell lung cancer samples." (PMID 24637157, 2014).
adult T cell leukemia (2 papers, 2017 to 2025). "Furthermore, adult T cell leukemia (ATL) cells were separately reported to suffer from reduced TDP1 expression." (PMID 39660638, 2025). "In fact, ABC has been used for treating adult T cell leukemia (ATL), since ATL cells are unable to efficiently eliminate mis-incorporated ABC from the 3′ end of primers due to a defect in tyrosyl-DNA phosphodiesterase 1 (TDP1)." (PMID 28380422, 2017).
ataxia telangiectasia (2 papers, 2016 to 2020). Ataxia-telangiectasia is the association of severe combined immunodeficiency (affecting mainly the humoral immune response) with progressive cerebellar ataxia. "Mutations in TDP1 play an important role in the development of neurodegenerative diseases such as ataxia telangiectasia (A-T) and spinocerebellar ataxia with axonal neuropathy (SCAN-1)." (PMID 31979371, 2020).
breast carcinoma (2 papers, 2021 to 2023). "DDR is regulated by multiple genes, among which TDP1 is present in breast cancer cells and plays an important role in repairing DNA damage." (PMID 34502549, 2021).
cerebellar degeneration (2 papers, 2009 to 2013). Degeneration of the cerebellum. "SCAN1 patients and Tdp1, knockout mice exhibit late onset cerebellar degeneration, pointing at an important role for TDP1 in non-dividing neural cells." (PMID 19303373, 2009).
glioma (2 papers, 2018 to 2021). A benign or malignant brain and spinal cord tumor that arises from glial cells (astrocytes, oligodendrocytes, ependymal cells). "The starting compound 1 was the most effective in the inhibition of TDP1 and compound 2 was the most effective in the sensitization of glioma T98G cells to TMZ." (PMID 34062881, 2021). "The synthesized compounds were able to inhibit TDP1 at micromolar concentrations (0.19–2.3 μM) and demonstrated low cytotoxicity in the T98G glioma cell line." (PMID 34062881, 2021). "Differently, modified U87 glioma cells lines presenting either Tdp1 overexpression or knockout did not reveal any significant changes in the expression patterns of PARP1 gene." (PMID 29597329, 2018).
small cell lung carcinoma (2 papers, 2019 to 2025). Small cell lung cancer (SCLC) is a highly aggressive malignant neoplasm, accounting for 10-15% of lung cancer cases, characterized byrapid growth, and early metastasis. "A study on small cell lung cancer (SCLC) cell lines found that TDP1/TOP1 protein ratio is a better predictor than the individual TDP1 or TOP1 protein level, showing good correlation with irinotecan sensitivity in eight out of ten cell lines examined." (PMID 31547492, 2019). "In addition, the application of TDP1 inhibitors has been explored in tumor resistant to TOP1 inhibitors, such as metastatic ovarian, cervical, and small-cell lung cancers." (PMID 40133672, 2025).
dementia (1 paper, 2012). Loss of intellectual abilities interfering with an individual's social and occupational functions. "Of the 27 sporadic cases, 9 were tau-positive (Pick's pathology) and 18 were tau-negative (13 TDP1, 3 ubiquitin-positive with unknown TDP status, 1 with neuronal intermediate filament inclusion disease [NIFID], and 1 with dementia lacking distinctive histology [DLDH])." (PMID 21596458, 2012).
emphysema (1 paper, 2023). "Interestingly, emphysema was present in various degrees in three out of four TDP1 variant carriers." (PMID 36769106, 2023). "When tissue from areas with mild and severe emphysema from the same patient was compared, the TDP1 level was lower in the more affected areas." (PMID 36769106, 2023).
Fanconi anemia (1 paper, 2022). Fanconi anemia (FA) is a hereditary DNA repair disorder characterized by progressive pancytopenia with bone marrow failure, variable congenital malformations and predisposition to develop hematological or solid tumors. "Besides ABCC4, POLE3, POLE4, and the Fanconi anemia pathway genes FANCF and C17orf70 are top candidates that sensitize both wild-type and TDP1-KO cells to CPT treatment." (PMID 35869071, 2022).
hereditary ataxia (1 paper, 2013). An instance of an atactic disorder that is caused by an inherited genomic modification in an individual. "This is typified by defects in tyrosyl DNA phosphodiesterase 1 (TDP1) and human hereditary ataxia." (PMID 23626666, 2013).
Hypoalbuminemia (1 paper, 2021). The concentration of albumin in the blood circulation is below the lower limit of normal. "Mouse Tdp1−/− models have been generated in attempts to unravel the physiological role of TDP1, but only a few mild phenotypes were reported in adult animals, such as a slight reduction in brain-to-body ratio and hypoalbuminemia." (PMID 33514542, 2021).
leishmaniasis (1 paper, 2019). Infectious disease that is transmitted through the bite of hematophagous female phlebotomine sand flies. "Furamidine is used to treat Trypanosomiasis and leishmaniasis, which express Tdp1, but it is unclear if Tdp1 inhibition is part of the antiparasitic activity." (PMID 31875206, 2019).
neurotoxicity (1 paper, 2024). Toxicity that causes injury to the central or peripheral nervous system or damages its function. "Neurotoxicity was also induced by inhibitors of the DNA damage response proteins TDP1 and ATM (167 and 50, respectively), indicating that DNA repair is essential for neuronal survival in culture." (PMID 38550989, 2024).
neutropenia (1 paper, 2012). A decrease in the number of neutrophils found in the blood. "In univariate analysis, SNPs in both Top 1 and TDP1 were associated with grade three out of four neutropenia." (PMID 22108516, 2012).
ovarian carcinoma (1 paper, 2019). A malignant neoplasm originating from the surface ovarian epithelium. "The results indicated that TDP1 deficiency promoted DNA damage and increased the chemosensitivity of ovarian cancer cells to carboplatin." (PMID 31235732, 2019). "The results indicated that miR-211 overexpression inhibited TDP1 expression, whereas suppressing miR-211 upregulated TDP1 expression in ovarian cancer cells." (PMID 31235732, 2019). "To verify that TDP1 is one of the key molecules that mediates the function of miR-211, we further detected the role of TDP1 in chemosensitivity and DNA damage in ovarian cancer cells." (PMID 31235732, 2019).
proteinopathies (1 paper, 2026). "Human TDP‐43 and C. elegans TDP‐1 constructs used to model proteinopathies in C. elegans." (PMID 40891506, 2026). "The nematode Caenorhabditis elegans, with highly conserved TDP‐43 orthologue TDP‐1, serves as a powerful genetic model to investigate the molecular underpinnings of TDP‐43 proteinopathies." (PMID 40891506, 2026).
pulmonary disease (1 paper, 2023). "We detected two previously unreported variants, one in TOM1L2 and one in TDP1, in multiple patients with pulmonary disease." (PMID 36769106, 2023).
cancer (63 papers, 2014 to 2025). A tumor composed of atypical neoplastic, often pleomorphic cells that invade other tissues. "Alagoz M., Wells O.S., El-Khamisy S.F. TDP1 deficiency sensitizeshuman cells to base damage via distinct topoisomerase I and PARPmechanisms with potential applications for cancer therapy." (PMID 41541557, 2025). "Several genome-wide screens have identified APE2 as a synthetic lethal target for deficiencies of BRCA1, BRCA2 or TDP1 in cancer cells." (PMID 36755963, 2023). "Tyrosyl-DNA phosphodiesterase 1 (TDP1) is an important target in cancer therapy because it repairs damaged 3′ ends of DNA caused by various drugs used commonly in cancer chemotherapy." (PMID 37298106, 2023). "TDP1 helps to prevent the DNA damage caused by Top1 inhibitors, hence TDP1 is responsible for drug resistance of some cancers." (PMID 36010892, 2022). "The mutations in TDP1 that result in reduction of its catalytic activity sensitizes cancer cells to the cytotoxic effects of TOPOI inhibitors." (PMID 36120345, 2022). "Dysregulation of Tdp1 protein levels or catalysis shifts the equilibrium to genome instability and is associated with driving human pathologies such as cancer and neurodegeneration." (PMID 31698852, 2019). "In contrast to CPT-resistant cancers, progressive accumulation of PDBs due to TDP1 deficiency leads to neurodegeneration." (PMID 29898404, 2018). "Disruption of TDP1’s ubiquitylation status causes neurological disease or resistance to topoisomerase I-targeting chemotherapy in cancer." (PMID 29898404, 2018). "A low level of UCHL3 is associated with reduced TDP1 protein levels, causing neurological disease, whereas its overexpression causes higher TDP1 levels in cancer." (PMID 29898404, 2018). "Here, using human MRC5 cells and cancer cell lines inherently deficient for TDP1 or resistant to alkylation-based chemotherapy, we show that TDP1 deficiency sensitizes human cells to base damage, independently of APE1." (PMID 24335147, 2014). "Later, it was shown that overexpression of TDP1 is associated with chromosomal instability and is observed in such types of cancer as non-small-cell lung cancer and colorectal cancer as well as in cell lines derived from breast cancer and some rhabdomyosarcomas." (PMID 36982848, 2023). "As TDP1-deficient cells show hypersensitivity to topoisomerase poisons, it is clinically appealing to combine well-established topoisomerase poisons with TDP1 inhibitor for cancer therapy." (PMID 35869071, 2022). "A number of studies confirmed the hypothesis that Tdp1 is responsible for the resistance of some types of cancer to these drugs: Tdp1-deficient human cells are hypersensitive to camptothecin." (PMID 32823658, 2020). "Thus, Tdp1 inhibition together with PARP1 inhibition is a successful treatment strategy taking advantage of additional impeding mutations that cancer cells maintain." (PMID 31875206, 2019). "The low expression of TDP1 observed in the GBM cell lines may reflect repair pathway deficiencies in cancer development." (PMID 31547492, 2019). "Because MiDAS is elevated in cells challenged with RS and is especially prevalent in aneuploid cancer cells with oncogene activation, inhibition of CDK1 may provide a therapeutic intervention in cancers with elevated TDP1 expression, which is known to cause chromosomal instability." (PMID 39014228, 2024). "The hypothesis that Tdp1 is responsible for the drug resistance of some types of cancer is supported by a number of studies: Tdp1 knockout mice and human cell lines that have a mutation that reduces the activity of this enzyme are hypersensitive to camptothecins." (PMID 38279210, 2024). "Importantly, since compounds inducing TOP1-mediated DPCs are currently used in cancer treatment, understanding the underlying mechanism of the repair pathway is essential for improving the efficiency of combination therapy with TDP1 and MUS81 inhibitors." (PMID 37194054, 2023).
cancer (continued). "The hypothesis that Tdp1 is responsible for drug resistance in some cancers is supported by a number of studies: Tdp1 deficiency in Tdp1 knockout mice and in human cell lines with a mutation, which reduces the activity of this enzyme, leads to hypersensitivity to camptothecin or its derivatives." (PMID 33808389, 2021). "The obtained data indicate that compound 6d enhances the action of Tpc specifically through the inhibition of TDP1 and emphasize the significance of this enzyme as a target for increasing the efficiency of cancer therapy with topoisomerase 1 inhibitor drugs." (PMID 41155491, 2025). "TDP1 is a promising molecular target in cancer therapy because it participates in the repair of many DNA adducts formed by chemotherapeutic drugs such as topotecan, etoposide, bleomycin, temozolomide." (PMID 41155491, 2025). "TDP1 andTOP1 modulation in olaparib-resistant cancer determines the efficacyof subsequent chemotherapy." (PMID 41541557, 2025). "Both components, the usnic acid derivative and the peptide, are selectively active against cancer cells, by targeting the human DNA repair enzyme tyrosyl-DNA phosphodiesterase 1 (TDP1) and through DNA damage, respectively." (PMID 39596476, 2024). "Despite the promise of Tdp1 as a target for novel cancer therapies, significant research gaps persist." (PMID 39338235, 2024). "Tyrosyl DNA phosphodiesterase 1 (Tdp1) is a promising target for cancer treatment because it plays a key role in removing DNA damage formed by camptothecin group compounds (irinotecan and topotecan), widely used in anticancer therapy." (PMID 38279210, 2024). "This allows for the safe, efficient identification of Tdp1 inhibitors, paving the way for personalized oncology treatments in the future by suppressing cancer growth." (PMID 39338235, 2024). "As Top1-mediated genomic lesions can disrupt DNA replication and subsequently inhibit cellular proliferation of cancer cells, Tdp1 inhibitors have been developed as potential cancer therapies." (PMID 39338235, 2024). "In the search for additional synthetic lethal targets, APE2 is over-expressed in many cancers and has emerged as a novel endonuclease that is required for the survival of cancer cells deficient in BRCA1, BRCA2 or TDP1." (PMID 37645072, 2023). "A possible therapeutic benefit of the combined use of such substances and TDP1 inhibitors is stronger suppression of cancer cell growth and/or a reduction in the dose of conventional chemotherapy." (PMID 36982848, 2023). "Differences under the action of treatment with TOP1 or TDP1 inhibitors alone were found in the signaling pathways for the development of cancer, DNA repair, and the proteasome." (PMID 36982223, 2023). "Given the importance of TOP1 inhibition in cancer therapy, the role of TDP1 in TOP1-DPCR has been extensively investigated in vitro and in cell cultures, but data on the vertebrate models are sparse." (PMID 37788708, 2023). "The function of TDP1 in the repair of cellular DPCs and histone-DPCs has not been previously investigated and our results should be considered in the development of TDP1 inhibitors for cancer therapy." (PMID 37788708, 2023). "Changes under the treatment with TOP1 and TDP1 inhibitors separately were found in the signaling pathways for the development of cancer, DNA repair, cell cycle control and apoptosis, and the proteasome." (PMID 36982223, 2023). "TDP1 plays a crucial role in the repair of DNA lesions formed by antitumor drugs such as the TOP1 inhibitors camptothecin, topotecan (a TOP1 poison in clinical use), and irinotecan; therefore, TDP1 is a promising target for adjunctive cancer treatment." (PMID 36982848, 2023). "TDP1 appears as a target in cancer drug design owing to its ability to sensitize tumor cells to the action of TOP1 poisons and to break down various DNA adducts induced by chemotherapeutics." (PMID 36982223, 2023).